CFH (complement factor H)
Diseases named in the same sentence as CFH in open-access papers (continued):
Sharing a sentence is not in itself a finding about the gene and the disease.
cancer (25 papers, 2002 to 2025). A tumor composed of atypical neoplastic, often pleomorphic cells that invade other tissues. "CFH is overexpressed on many different types of cancer cells and is usually associated with poor prognosis." (PMID 38389705, 2024). "We observed that individual LC-associated proteins, such as complement component 9 (C9), C4b-binding protein (C4BP), α2-HS-glycoprotein, and CFH, display both cancer-associated and neutral epitopes." (PMID 37211046, 2023). "In a chemically induced carcinogenesis model of PTX3‐deficient mice, defective recruitment of CFH to cancer cells results in higher levels of the anaphylatoxins C3a and C5a due to complement activation." (PMID 33708358, 2020). "CFH is a regulatory component of the complement cascade which affects cell mediated immune responses and increases in complement proteins are associated with poor outcomes in multiple cancer types." (PMID 35223500, 2022). "CFH is the dominant serum complement regulatory protein of the alternative pathway and influences multiple human diseases including cancer." (PMID 39747856, 2025). "While CFH is predominately produced in the liver, multiple human cancer cell types express and bind CFH, resulting in resistance to complement-mediated lysis and promotion of local immunosuppression." (PMID 39747856, 2025). "Through its control of the complement system, interactions with immune cells, and effects on the TME, complement factor H contributes significantly to immune evasion in cancer." (PMID 38389705, 2024). "The formation of the membrane attack complex (MAC) and consequent cell lysis are both prevented by CFH’s ability to attach to the surfaces of cancer cells and suppress complement activation." (PMID 38389705, 2024). "This review explores the molecular underpinnings, interactions with immune cells, clinical consequences, and therapeutic possibilities of CFH as an innate immune checkpoint in cancer control." (PMID 38389705, 2024). "To further identify cancer‐predisposing SNVs, we screened COSMIC‐documented loci, leading to the identification of the SNVs DNAH11 c.9463G > A (p.Ala3155Thr) and CFH c.2314G > A (p.Asp772Asn) in the COSMIC database." (PMID 38970307, 2024). "CFH has been found to interfere with antigen presentation, a critical step at the beginning of adaptive immune responses against cancer cells." (PMID 38389705, 2024). "CFH is required to maintain cancer stemness via late SV40 factor that regulates thymidylate synthase gene, thus contributing to cell cycle regulation." (PMID 38970307, 2024). "In summary, CFH mediates immune evasion by cancer cells through a variety of cellular and molecular pathways." (PMID 38389705, 2024). "In conclusion, a three‐generation family with three members affected by different types of cancer was found to have multiple germline predisposition genes, including DNAH11 and CFH." (PMID 38970307, 2024). "Although the complex role of CFH in cancer cells underscores the importance of further investigation of complement in the immune surveillance of cancers." (PMID 35223500, 2022). "Data presented here helps to solidify the relationship between CFH and tumorigenesis but they also raise many questions about the role of CFH in cancer progression." (PMID 35223500, 2022). "In the context of cancers, cancer cells have been shown to make use of CFH to reduce complement activation in their microenvironment." (PMID 33708358, 2020). "CFH expression was detected in three out of five adjacent normal lung and cancer tissues where STATs are expressed." (PMID 30987235, 2019). "Our results showed STAT1 levels were higher in cancer tissues #3 and #4S, while STAT3 levels were higher in cancer tissues #3, #4, and #5, but the correlation with CFH expression was weaker than that of STAT4." (PMID 30987235, 2019). "Several cancer types show dysregulated expression of complement factor H (CFH)." (PMID 39747856, 2025). "CFH is a key component in the process of cancer immune evasion." (PMID 38389705, 2024).
cancer (continued). "Use of monoclonal antibodies (mAbs) designed to specifically target CFH could neutralize its immunosuppressive effects and inhibit cancer progression." (PMID 38389705, 2024). "CFH binds to C3b and thus prevents C3b from adhering to cancer cells and inhibiting phagocytosis." (PMID 38389705, 2024). "CFH dysregulation in cancer has significant implications for clinical outcomes." (PMID 38389705, 2024). "This has been illustrated in murine models of cancer with targeted deletion of the CFH." (PMID 35860237, 2022). "CFH is overexpressed in cancers, which allows cancer cells to avoid complement-mediated attack." (PMID 30987235, 2019). "Although many reports have demonstrated CFH’s expression, functions, and complex interactions with other regulatory proteins in the complement system, no information is known about the molecular mechanisms of CFH expression in cancers." (PMID 30987235, 2019). "Multiple strategies could be used for targeting CFH for anti-cancer therapies." (PMID 38389705, 2024). "Thus, the inhibition of CFH in cancer cells may improve anticancer therapy." (PMID 30987235, 2019). "In A549 cells and cancer tissues #3 and #4, STAT4 expression was higher in the tissues that also had a high expression of CFH." (PMID 30987235, 2019). "In our program we previously reported IgG autoantibodies targeting complement factor H (CFH) to be associated with early stage, non-metastatic NSCLC and increased time to recurrence, conceptually conferring a protective effect against cancer progression." (PMID 39747856, 2025). "Complement factor H (CFH), predominately known for its function in inhibiting the alternative pathway of the complement system, has recently been identified as an important innate immunological checkpoint in cancer." (PMID 38389705, 2024). "Importantly, cancer patients with CFH autoantibodies demonstrate no obvious detrimental phenotype." (PMID 39747856, 2025). "However, CFH was not amplified in two normal and one cancer tissues that did not express STATs." (PMID 30987235, 2019).
renal disease (25 papers, 2011 to 2025). "Patients with genetic deficiency or abnormalities in complement factor H (FH)—the main regulator of the alternative pathway of complement—develop renal disease that progresses to end-stage renal disease." (PMID 34112227, 2021). "Accordingly, renal diseases have been reported in 28 out of 33 individuals with inherited complete deficiency of CFH." (PMID 31354740, 2019). "Notably, a pathogenic haplotype in the CFH gene family is associated with different kidney diseases." (PMID 28729648, 2017). "Interestingly, individuals with other genetic defects within the CFH gene family are susceptible to exacerbation of kidney disease during throat infections." (PMID 22503529, 2012). "The importance of cell surface recognition by CFH is well-illustrated in a study showing that mice with a mutant CFH that lack its surface recognition domains (including an MDA-binding site) develop spontaneous kidney disease." (PMID 31354740, 2019). "Complement factor H (CFH), as a regulator of the complement alternative pathway, is also associated with various renal diseases." (PMID 27113631, 2016). "While aged Cfh−/− mice developed spontaneous renal disease with omnipresent deposition of complement components on the glomeruli, CFH deficient mice lacking B cells were protected from renal damage." (PMID 31354740, 2019). "CFH was documented to play protective roles against multiple renal diseases." (PMID 24596580, 2014). "In addition, several important renal disease-causing genes such as the major genes for ADPKD (PKD1) and aHUS (CFH and its related CFHR genes) are located in the most genomically complex regions that require a specific targeted design in order to not miss any disease-causing variant in these genes." (PMID 33712733, 2021). "There exists a well-recognized genotype–phenotype correlation with respect to CFH variants and disease, with variants affecting CCP domains 1 through 4 and CCP domains 6 through 8 mainly causing eye disease, whereas those affecting CCP domains 19 and 20 causing kidney disease." (PMID 30905644, 2019). "Therefore, we speculate that from the genetic polymorphism of CFH Y402H, reduced binding of C-reactive protein to the CFH protein limits the function of CFH, which results in the development of AMD and kidney disease." (PMID 36604459, 2023).
infectious disease (7 papers, 2012 to 2023). A disorder directly resulting from the presence and activity of a microbial, viral, or parasitic agent in humans. "CFH deficiency has been observed to be associated with several glomerular and infectious diseases, including aHUS, C3G and acute infections with Neisseria meningitides, etc.." (PMID 37322353, 2023). "It seems that the clinical expression of the homozygous MCPggaac haplotype depends significantly on additional mutations in the aHUS spectrum, especially CFH and CFI, and if so, various infectious diseases or even drugs trigger aHUS in children who are genetically prone to aHUS onset." (PMID 37685848, 2023).
genetic disease (6 papers, 2012 to 2023). "CFH was the first protein to be associated with genetic disease, followed by CFI and MCP, and then by C3/C3b." (PMID 25188723, 2014). "The biochemical mechanism of CFH-associated genetic disease may involve either the facilitation of CFH aggregation to form pathogenic deposits, or the biochemical loss of CFH regulatory control." (PMID 24744754, 2014). "In this study, we found that in 45 children diagnosed with aHUS, genetic disorders in complement-regulating genes encoding CFH, CFI, MCP, CFB, C3, and THBD, as well as the presence of αFH with or without a homozygous deletion in CFHR1/3, are linked with clinical presentation, treatment, and outcome." (PMID 22410797, 2012). "Through our analysis of CFH, rhodopsin, and RPE65, we were able both to draw conclusions relating to critical residues in protein structures and to predict misfolding-causing mutations in genetic disease." (PMID 27905547, 2016). "In CFH-associated genetic diseases such as AMD and aHUS, the CFH–heparin interaction may be affected by polymorphisms or mutations." (PMID 24744754, 2014).
bacterial infection (5 papers, 2014 to 2023). "Interestingly, genetic polymorphisms in this region are associated with susceptibility to several bacterial diseases and CFH and CFHR proteins are targets for pathogen modulation." (PMID 37928534, 2023). "Proteins predictive of ABM include CATD and complement factor H (CFAH), both of which are known plasma proteins involved in clearance of specifically bacterial infections." (PMID 33821792, 2021).
degenerative disease (4 papers, 2008 to 2021). "MIR155 overexpression was previously implicated in downregulation of complement factor H (CFH) expression in AD and other neurodegenerative diseases which in turn may prevent spontaneous immune system activation." (PMID 30636644, 2019).
immune disease (4 papers, 2014 to 2019). "In addition to age, immune dysfunction as demonstrated by the complement factor H (CFH) risk allele (Y402H) and environmental factors, in particular smoking, are also risk factors for AMD." (PMID 29762536, 2018). "Defective interactions at either of the two independent CFH–heparin sites reduce the CFH interaction with surface-bound C3b and lead to immune disorders." (PMID 24744754, 2014). "Based on a review of related literature, CFH and clusterin might be related to immune diseases, and thus they were chosen for further verification." (PMID 31708932, 2019). "It is not clear at present why a polymorphism at SCR-7 in CFH leads to one immune disease, while mutations at SCR-19/20 lead to a different disease altogether." (PMID 24744754, 2014). "Starting from the first reports of complement disease-associated mutations, genetic alterations in four CFH (complement factor H), CFI (complement factor I), MCP (membrane cofactor protein) and complement C3 have increasingly been associated with immune disorders." (PMID 25188723, 2014).
neurological disease (4 papers, 2020 to 2023). "In addition, miR-146a participates in the neuroinflammatory response of different neurological diseases by regulating the common inflammation-related target genes (IRAK1, TRAF6, and CFH) and related pathways (TLR signaling pathway and complement activation pathway)." (PMID 32581706, 2020).
retinopathy (3 papers, 2013 to 2020). "This single case describes the favorable visual outcome achieved after systemic treatment with eculizumab in a patient with severe Purtscher-like retinopathy secondary to familial aHUS and CFH mutation." (PMID 28275964, 2018).
heart disease (1 paper, 2020). "For example, while CDK13, CHD4, KDM5A, and SCN10A are related to familial heart disease, CFH, DGUOK, and POLE are related to familial vascular disease." (PMID 31941532, 2020).
metabolic disease (1 paper, 2023). A congenital disorder (due to inherited enzyme abnormality) or acquired (due to failure of a metabolically important organ) disorder resulting from an abnormal metabolic process. "We hypothesized that CFH might cause the peroxisome-generated succinate to be produced, which would lead to DKD and other metabolic diseases." (PMID 37063851, 2023).
overlap syndrome (1 paper, 2023). "One case reported a very rare overlap syndrome: the patient had auto-antibodies against ADAMTS13 and against CFH; one case was a hereditary TTP; two recent cases were i-TTP with heterozygous variants of CFH, CFI and C3." (PMID 36769407, 2023).
CFH also shares sentences with these, for which no sentence is quoted: Blindness (6 papers); cardiovascular disease (5); neovascular age-related macular degeneration (4); pneumococcal meningitis (4); glomerulopathy (3); Neuromyelitis Optica Spectrum Disorder (3); Polypoidal choroidal vasculopathy (3); rheumatoid arthritis (3); ANCA-associated vasculitis (2); antiphospholipid antibody syndrome (2); choroidal neovascularization (2); dyslipidemia (2); hyperthyroidism (2); IgG4-Related Disease (2); inborn error of immunity (2); influenza (2); liver disease (2); monoclonal gammopathy (2); pituitary adenoma (2); prion disease (2); renal cell carcinoma (2); Renal Dysfunction (2); abortion (1); acute coronary syndrome (1); Adult onset (1); Allergy (1); amyloidosis (1); Arthritis (1); autism (1); autoimmune hepatitis (1).
A further 83 diseases each share a sentence with CFH in 1 paper.